CD4 (CD4 molecule)
Diseases named in the same sentence as CD4 in open-access papers (continued):
Sharing a sentence is not in itself a finding about the gene and the disease.
tumor (continued). "It was reported by us and others that TNFR2 could be expressed by mouse antigen-experienced CD4+Foxp3- conventional T cells, including those in the tumor environment, we thus firstly analyzed TNFR2 expression by subsets of cells in CD4 T cell metaclusters." (PMID 36865537, 2023). "Contrarily to these effects, Th2 and Th17 CD4+ T cells are also thought to have pro-tumorigenic activities mainly involving induction of cytokines that can promote growth, proliferation, and invasion of tumor cells, including IL-4 and IL-17, respectively." (PMID 37529610, 2023). "The necessity of TOX for CD4 lineage development suggests that its abnormal expression may lead to clonal proliferation of malignant T tumor cells." (PMID 36969216, 2023). "We performed mass cytometry and identified nine immune cell populations, namely, in CD45+ (tumor-infiltrating lymphocytes) TILs, including B cells, CD4+ T cells, CD8+ T cells, DCs, γδ T cells, macrophages/monocytes, neutrophils, NK cells, and NKT cells using canonical marker level measurements." (PMID 37525249, 2023). "Apart from CD8+ T cells, CD4+ T cells are essential for tumor elimination." (PMID 37513975, 2023). "We next assessed whether the potent antitumor effect of IBI315 is due to higher immune cell infiltration and quantified the CD3+, CD8+, and CD4+ tumor‐infiltrating lymphocytes in the xenografts." (PMID 37587833, 2023). "Additionally, in lung cancer and melanoma, the presence of tumour infiltrating lymphocytes and increased gene expression for CD4 and CD8 was found to correlate with improved survival in those patients treated with immunotherapy." (PMID 37143952, 2023). "However, in two by two comparisons, CD4+cells in some Tumor stages (T1 vs T3, **, p=0.006) and pTNM stages (I vs II **, p=0.004, I vs IV, * p=0.04) were statistically significant." (PMID 36891293, 2023). "Our results indicate the need for further investigation into the role of CD4+ CTLs and DN B cells as potential drivers or inhibitors of tumor immunity, which could enable the development of a novel cancer immunotherapeutic strategy." (PMID 38077321, 2023). "Surprisingly, the high-risk group demonstrated a greater presence of plasma cells, CD8+ T cells, memory-activated CD4+ T cells, follicular helper T cells, and regulatory T cells, accompanied by a higher immune score, thus warranting classification as a “hot” tumor phenotype." (PMID 37762031, 2023). "We reasoned, therefore, that anchoring the immunogenic fragment of KRASG12V to the plasma membrane of tumor cells may enable direct antigen recognition by CD4+ T cells." (PMID 36512410, 2023). "Furthermore, through the ectopic expression of LMP1 on patient-derived tumor B cells to prime T cells, autologous cytotoxic CD4+ T cells can be expanded to target a wide range of endogenous tumor antigens, including TAAs and neoantigens." (PMID 37841280, 2023). "In our evaluation of tumour-infiltrating lymphocytes (TILs) and Foxp3 expression in tumour tissues using immunohistochemistry (IHC) in 358 patients, patients with high levels of CD4 + T cells or CD8 + T cells exhibited better prognosis (all p < 0.05)." (PMID 37582713, 2023). "We also identified a subgroup of HLA-DRhigh CD206+ TAM that may interact with tumor-infiltrating CD4 + T and may be a potential therapeutic target for LSCC." (PMID 36864443, 2023). "CTLA-4 is an inhibitory co-receptor constitutively present on Tregs, which plays an important role in regulating CD4+ T cell function, and in HCC, as in other cancer types, it inhibits T cell proliferation through the recognition and differentiation of tumor-associated antigens." (PMID 36769116, 2023). "CD4+T cells exert an important role in tumor immune surveillance." (PMID 37089050, 2023). "After sacrificing the tumor-bearing mice, the spleen was made into single-cell suspension, CD4+T cells were isolated and purified by immunomagnetic beads in vitro, so that purity could meet the requirements of subsequent experiments." (PMID 37274637, 2023).
tumor (continued). "In addition, N-809 reduced the frequency of immunosuppressive regulatory T cells (defined as CD4+ FoxP3+ T cells) in the tumor environment." (PMID 37616311, 2023). "Antigen presentation was carried out mainly by migratory and dLN-resident conventional type 2 DCs (cDC2s) and significantly more potent antitumor responses were triggered in both prophylactic and therapeutic tumor models in a CD4+ and CD8+ T cell-dependent fashion." (PMID 37455272, 2023). "Additionally, FMRP KO or knockdown enhanced the ability of CD8 and CD4 T cells to kill tumor cell measured by in vitro co‐culture killing experiments." (PMID 36968189, 2023). "In addition, many reports have shown that mixed CD4+/CD8+ CAR-T populations are more effective in controlling in vivo tumour growth than CD8+ CAR-T cells administered alone." (PMID 37684239, 2023). "Tumor tissue carried most cellular components such as cancer cells, T cells, B cells, and endothelial cells, among which macrophage had the highest percentages, following CD4+ and CD8+ T cells." (PMID 37889543, 2023). "The checkpoint molecules are mostly expressed in the sclerotic tumor and the tumor, suggesting immune checkpoint therapy could have a possible effect here by releasing the blocked CD4 and CD8 cells." (PMID 36980192, 2023). "Our results indicate that the anti-tumor function of the CD4+ T cells, especially CD4+ Th1 cells, was significantly enhanced by Emut Vax, together with the complex cytokine network that may control the transdifferentiation of different T helper lineages." (PMID 36875137, 2023). "Although these results could not explain directly the role of IL-17A+ inflammatory cells in tumor development, increased GC development in MNU and H. pylori-treated mice was associated with an elevated number of CD4+ and CD8+ cells." (PMID 36125689, 2023). "Specific CD4+ T cell populations also mediated tumor killing and regression." (PMID 38102684, 2023). "Notably, the potential of targeting HLA class II-restricted antigens was recently underscored by clinical data on the crucial role of HLA class II and CD4 + T cells in immune-mediated tumor rejection." (PMID 37368072, 2023). "Meanwhile, after combination therapy, a higher population of CD4+ Th1 subsets was observed compared to the tumor-bearing control and cryo-thermal therapy groups, which suggested that combination therapy further enhanced Th1-dominant CD4+ T-cell differentiation induced by cryo-thermal therapy." (PMID 37108179, 2023). "On the other hand, in early non-small-cell lung cancer (NSCLC), neutrophils which express OX40 ligand, CD86 and 4-1BB ligand could assist the activation of CD4+ T cells to defense tumor cells." (PMID 36934105, 2023). "Moreover, both E7 proteins mixed or coupled with Qβ-VLPs were effective in inducing strong CD8 and CD4 T-cell responses and significantly reducing tumor growth of TC-1 cells expressing HPV16 E7 oncoprotein in C57BL/6 female mice." (PMID 37629147, 2023). "Besides being highly tumor-specific, NGcGM3 is known to harbor immune-suppressive activities through down-regulation of CD4 Ag, and is therefore considered to be an ideal target for cancer immunotherapy." (PMID 36679991, 2023). "Circulating CD4 T cells are often the first to migrate to the tumour site." (PMID 38567060, 2023). "Engagement of TLRs on dendritic cells (DCs) promotes cross-talk between the innate and the adoptive immune system, maturation and migration of DCs into lymph nodes leading to activation, and proliferation and survival of tumor antigen-specific naïve CD4+ and CD8+ T cells." (PMID 36775056, 2023). "Overall, the frequency of CD56 was low on tumor-derived and spleen-derived CD4+ MSLN-CAR T cells." (PMID 36746513, 2023). "Furthermore, in the primary tumor, the percentage of regulatory T (Treg, CD4+Foxp3+) cells is greatly reduced by the ICIE treatment." (PMID 36693842, 2023). "Conversely, CD4+ Tregs can reduce anti-tumor immunity and accelerate its progression." (PMID 36833428, 2023).
tumor (continued). "We found that, besides being a tumor with limited lymphocyte infiltration, there was a selective enrichment for CD4+ T lymphocytes, while CD8+ T cells and B cells were selectively depleted, indicating a complex biological role for infiltrating immune cells in PC development and/or progression." (PMID 36811045, 2023). "Furthermore, the fusion of immune adjuvant with hGLV facilitated the maturation of DC cells, which in turn increased the infiltration of CD8 + and CD4 + T cells in tumors, resulting in improved anti-tumor immunity." (PMID 38087360, 2023). "Although Th2 cells may promote tumor development through immunosuppression, the subtype closest to immunosuppression in CD4+T cells is Treg." (PMID 38264667, 2023). "However, as demonstrated in this study, CD4 T cells can mount effective anti-tumor immune responses." (PMID 37711623, 2023). "Synthesized nanoparticles may restructure and restore tumor blood vessels, reduce tumor hypoxia, increase the percentage of CD4+ and CD8+ T cells of tumors tissue, and induce macrophage polarization, according to extensive testing and histological stains." (PMID 36903458, 2023). "For example, in mouse models of CRC, colonization by Helicobacter hepaticus induced an increase in the number of colonic CD4 Tfh cells and promoted the maturation of tumor-adjacent tertiary lymphoid structures, increased cytotoxic lymphocyte infiltration in tumor, and inhibited tumor growth." (PMID 36950522, 2023). "Thus, it is significant to strength the study of the mechanism of CD4+ T cells recognizing and killing tumor cell to obtain optimal antitumor responses." (PMID 37287989, 2023). "Lastly, we found increased frequency of Ki-67+ CD8+ and CD4+ T cells in the tumor, indicative of their increased activation in the absence of suppressive signals provided by Tregs, potentially explaining the increased frequency of circulating T cells we observed in the tumor and circulation." (PMID 37089449, 2023). "Targeting the TGF-β pathway in CD4+ T cells may inhibit tumor growth by remodeling and normalizing the tumor vascular network." (PMID 38193080, 2023). "CD4+ T cell can infiltrate and recognize autologous tumor in a MHC II-restricted manner." (PMID 37287989, 2023). "Furthermore, the specific high expression of CXCL13 and CXCR5 in PD1+CD4+ T cells was observed in tumour tissues as well as adjacent tissues." (PMID 36855810, 2023). "Polarization of CD4+ T cells also plays a part in tumor formation and growth." (PMID 37445860, 2023). "Notably, immunofluorescence results of tumor tissues showed a dramatic increase in CD4+ or CD8+ T cell infiltration in the Nano-CD & αPD-1 group, implying the superior performance of immune activation." (PMID 36774382, 2023). "Overall, our results suggest that only certain antigens are presented directly on MHC-II+ tumor cells, which may limit the pool of CD4+ T cells capable of directly recognizing and eliminating tumor cells." (PMID 36512410, 2023). "In addition to an immunosuppressive role, it was recently found that CD4+ T-cells also play an important role in anti-tumor immunity in BC." (PMID 37727793, 2023). "When comparing peripheral blood and tumor infiltrate, we found a significant increase of CD4+ lymphocytes and monocytes in peripheral blood, while the percentage of CD8+ T lymphocytes and myeloid-derived suppressor cells (MDSCs) was significantly higher in tumors." (PMID 36900156, 2023). "CD8+ T cells may inhibit tumor growth and induce tumor cell apoptosis through cytotoxic effects, while CD4+ T cells can secrete cytokines necessary for the growth and proliferation of CD8+ T cells." (PMID 37325889, 2023).
tumor (continued). "However, mice that received CD4 T cells from ITI-3000-immunized IFNγ-/- mice showed tumor kinetics and overall survival equivalent to that of mice that received CD4 T cells from control-immunized mice." (PMID 37711623, 2023). "However, PD-1 blockade significantly reduced HCC development in Chatfl/fl; Cd4-cre mice, substantially eliminating the differences in tumor progression." (PMID 37640929, 2023). "The killing effect of BCR and some costimulatory molecules, such as CD40 and CD86, on the surface of B cells in response to external antigen stimulation or enhancement of costimulatory signals of CD4+ T cells in tumours can also be used as markers for clinical prognostic monitoring." (PMID 36890557, 2023). "The panel could detect subsets of monocytes expressing CD14 and MHC-II or CD4 and demonstrated that neutrophils in the tumor were characterized as CD14–MHCII–CD4+." (PMID 36996049, 2023). "However, increased quantities of tumour-infiltrating lymphocytes (TLSs, CD4+T cells, and CD8+T cells) are related to a good prognosis." (PMID 37691922, 2023). "In addition, anti-ICOS treatment of tumor-bearing mice increased IL-17A expression by CD4+ T cells in the lung." (PMID 36480166, 2023). "The relationship between the tumor-infiltrating CD4+ T cells and survival was also assessed." (PMID 37771774, 2023). "Likewise, its tumor suppressor effects are associated with the reduction of myeloid-derived suppressor cells and regulatory T cells and the infiltration of antitumor immune cells: CD8+T cells, CD4+T cells, and M1 macrophage in the tumor microenvironment." (PMID 37936608, 2023). "Mechanisms, how CD4+ T cells can contribute to anti-tumor immunity have been described." (PMID 36776340, 2023). "Consequently, the T cell–unfavorable tumor microenvironment in liver metastasis was reshaped, as evidenced by abundant intratumoral infiltration of CD4+ and CD8+ T cells in E. coli–sgMafb/Maf–treated mice compared with E. coli–vector–treated mice." (PMID 36821387, 2023). "This may indicate that other signaling pathways are activated during the early stages of cSCC formation, leading to a significant increase in CD4+T cell infiltration and exerting anti-tumor effects." (PMID 37974224, 2023). "We also identified that the frequencies of subsets of tumor cells, CD4+ T cells, CD45RO+, stroma, and CD68+ macrophages, which are selected by S3-CIMA compared with non-selected cells from the same cell types, are significantly higher in the DII than in the CLR group." (PMID 37720335, 2023). "MHC class II expression in tumor cells increases antigen presentation to prime infiltrating CD4+ T cells, and decreased tumor cell MHC class II expression may result in immune escape." (PMID 38136348, 2023). "Additionally, in the treatment of neuroblastoma, anlotinib was found to improve the efficacy of anti-PD-1 mAbs by promoting vascular normalization via CD4+ T cells and by improving the immunosuppressive microenvironment within the tumor." (PMID 37055849, 2023). "In this scenario, Tregs might still use other mechanisms of suppression to regulate other cell types, such as effector CD4+ T cells, which can also contribute to tumor clearance." (PMID 37827864, 2023). "We hypothesized that SC-2 CD4+ cells with high CXCL13 expression might also regulate anti-tumor immunity by assisting TLS formation." (PMID 36049666, 2023). "The expression level distribution of immune scores in clusters 1 and 2 indicated that the percentage abundance of tumor-infiltrating immune cells (T cell CD4+, endothelial cell, and T cell CD8+) was significantly decreased in cluster 1, but Macrophage and NK cell were significantly opposite." (PMID 37945610, 2023). "We have previously shown in a humanized mouse model recapitulating EBV+ PTLD that two immunologic hallmarks associated with tumor progression are the increased expression of activation/exhaustion markers on CD8+ T cells (PD-1, LAG-3, and TIM-3) and accumulation of CD4+ Tregs." (PMID 37033919, 2023).
tumor (continued). "Tumor regression was dependent on CD4+ and CD8+ T cell responses and resulted in T cell memory." (PMID 37087494, 2023). "CD4+ T cells can act as recruiters and stimulators of anti-tumor response in cancer immunotherapy." (PMID 36960067, 2023). "CD8+ T cells along with CD4+ T cells are contributed to adaptive immunity and anti-tumor immunity." (PMID 38095640, 2023). "This inner tumor core also contained high levels of macrophage/monocytes and CD4+ and CD8+ T-cells." (PMID 37704757, 2023). "Moreover, compared to control-treated tumours, the combination of α-PD-1 and PARP14i demonstrated a significant increase of CD4+ and CD8 + T cells expressing surface inhibitory receptors PD-1, TIM-3, and LAG-3." (PMID 37752135, 2023). "The results of tumor microenvironment in the two groups revealed that patients with low-risk scores exhibited a higher proportion of CD8+ T cells, regulatory T cells, and memory CD4+ T cells and lower proportion of M0 macrophage." (PMID 37465666, 2023). "Additionally, in LUAD, the expression of KCNA3 seemed to be positively associated with the infiltration of immune subtypes that promote the anti-tumor response (Monocytes, CD4+ T cells, Mast cells, Dendritic cells) and are inversely related to M2 macrophages." (PMID 36978819, 2023). "Importantly, expression of PD-1 on CD8+ and CD4+ T cells in tumor-draining lymph nodes increased upon combination therapy, indicating an abundance of tumor-specific T cells after local RT and BRD4 inhibition." (PMID 37685868, 2023). "Thus, closer to the tumor cells, there are relative more macrophages, more M2 macrophages and relative more CD4 T cells and less B lymphocytes and CD8 T cells, suggesting an immune-suppressive environment." (PMID 37938368, 2023). "The reduced tumor growth in the combination group was also associated with a trend or significant increase in the % of tumor infiltrating CD3+, CD4+ and CD8+ T cells (respectively) and an increase in the proliferation index (Ki-67 expression) of CD3+ and CD8+ T cell subsets (respectively)." (PMID 37701441, 2023). "Furthermore, TRIM21 was reported to be highly expressed in immune cells, such as B cells, CD4 + T cells, macrophages, neutrophils, and dendritic cells, through the Tumor Immune Estimation Resource (TIMER) database." (PMID 36694250, 2023). "Since majority of the clinical data for virtual patient generation and model validation (e.g., CD8 and CD4 T cell density) were collected from tumor samples, the model was best trained to describe immune cell dynamics in the tumor compartment, which is therefore the focus of the following analyses." (PMID 37291190, 2023). "Consequently, the effectiveness of CD4+ T helper (Th1 lymphocytes) activation is decreased, as is the cytotoxic tumour cell killing reaction by CD8+ cytotoxic cells (CTLs)." (PMID 36980527, 2023). "Moreover, low‐Pi stress enhanced antitumour immunity and halted tumour progression by promoting the infiltration of CD4+ & CD8 + T cells, and inhibiting the infiltration of Tregs in murine models." (PMID 37471521, 2023). "CD4+ T cells have been described to contribute to anti-tumor immunity through a variety of mechanisms including direct killing of tumor cells, augmenting the tumor microenvironment through local secretion of effector cytokines, and providing help to CD8+ T cells." (PMID 38196632, 2023). "Regulation of cytotoxic functions of CD4+ T cells may therefore be of special interest in tumor therapy or chronic infections with T cell-based approaches." (PMID 36756120, 2023). "G9a knockdown remarkably increased the percentage of CD8+ and CD4+ T cells in tumor tissues." (PMID 36971192, 2023).